SLC31A1 (solute carrier family 31 member 1)
Diseases named in the same sentence as SLC31A1 in open-access papers (continued):
Sharing a sentence is not in itself a finding about the gene and the disease.
glioma (continued). "We used the data from the GEO database to examine the differences in SLC31A1 expression levels between glioma and normal tissues." (PMID 37610668, 2023). "As we analyzed, the high-SLC31A1 group glioma patients had worse outcomes than those with lower SLC31A1 gene expression levels." (PMID 37610668, 2023). "The in vitro KD experiment shows the SLC31A1 knockdown depressed the glioma cell proliferation and migration and promoted the apoptosis rate." (PMID 37610668, 2023). "The Cancer Genome Atlas (TCGA) and the Genotype-Tissue Expression (GTEx) were used to screen for SLC31A1 gene expression in glioma and healthy tissue samples." (PMID 37610668, 2023). "A high SLC31A1 gene level is related to infiltrating immune cell changes in glioma tissues, indicating a dismal prognosis." (PMID 37610668, 2023). "Following that, a clinical prognostic risk score for glioma was created using age, WHO grade, IDH status, 1p/19q codeletion, primary therapy outcome, and SLC31A1 expression." (PMID 37610668, 2023). "As SLC31A1 is crucial in glioma, we then tested the SLC31A1 gene function by in vitro experiments using LN229 and U251 cell lines." (PMID 37610668, 2023). "To better understand the functions of the SLC31A1 gene in glioma, we analyzed the genes related to the SLC31A1 by the STRING network." (PMID 37610668, 2023). "To better understand the biological role of the SLC31A1 gene in glioma, we analyzed the whole-genome profile of glioma patients from TCGA." (PMID 37610668, 2023). "The authors restored the expression of miR-375 and observed significant suppression in glioma cells proliferation, migration, and invasion, as well as the increase in the rate of adult glioma cell apoptosis by targeting SLC31A1." (PMID 37444408, 2023). "The results of IHC revealed that the expression level of SLC31A1 in high-grade glioma was significantly higher than in low-grade glioma, and ATP7B was lower in high-grade glioma, which was in line with the results from sequencing." (PMID 36267281, 2022). "They demonstrated that exosomal miR-375 decreased the progression of glioma cells through suppress Solute Carrier Family 31 Member 1 (SLC31A1) and is suitable for the treatment of glioma." (PMID 36536420, 2022). "Human BM-MSC exosomal miR-375 inhibits glioma cell progression through solute carrier family 31 member 1(SLC31A1)inhibition." (PMID 36727049, 2022). "Furthermore, glioma patients exhibit heightened SLC31A1 expression levels, which inversely correlate with key survival metrics including overall survival (OS), progression-free survival, and disease-specific survival." (PMID 41216190, 2025). "Costaining revealed elevated GFAP+-SLC31A1+, GFAP+-FDX1+, GFAP+-DLAT+, and GFAP+-DLST+ astrocytes in DSF-treated ECM mice, consistent with reports linking copper overload (e.g., via FDX1/SLC31A1 upregulation) to glioma progression and copper/zinc ionophores (e.g., CPT/ZPT) to astrocyte toxicity." (PMID 41214704, 2025). "Furthermore, the expression of SLC31A1 was increased in gliomas compared to healthy tissue, and the expression correlated significantly with a worse prognosis." (PMID 39062119, 2024). "The high SLC31A1 expression level strongly correlates with bad outcomes in glioma patients." (PMID 37610668, 2023). "Based on the previous data, it has been found that SLC31A1 is upmodulated in glioma patients." (PMID 37610668, 2023). "After that, we sorted the top 40 genes that mostly correlate with the SLC31A1 gene in glioma." (PMID 37610668, 2023). "The SLC31A1 gene expression can shorten the survival time of glioma patients." (PMID 37610668, 2023). "This means the SLC31A1 may promote glioma progression by enhancing the proliferation and migration of glioma cells." (PMID 37610668, 2023). "We verified the correlation among FDX1, SLC31A1, and macrophage infiltration in 56 glioma tissues." (PMID 37515314, 2023).
glioma (continued). "We found that the SLC31A1 expression level is lower in the IDH mutation group and 1p/19q codeletion group, which means that the SLC31A1 might influence the outcomes of glioma patients by influencing IDH mutation and 1p/19q codeletion." (PMID 37610668, 2023). "We used 2 × RealStar Green Fast Mixture qPCR kit (GenStar, Cat: A301-101) to analyze the expression of the SLC31A1 gene in different glioma cell lines, in which GAPDH was used as the housekeeping gene, and its reliability was determined by the computational program RefFinder." (PMID 37610668, 2023). "Among them, the Th2 and macrophage cells are the most relevant cells, which shows that the SLC31A1 gene may have a strong influence on the TME of glioma." (PMID 37610668, 2023). "The results also show that the SLC31A1 might be a critical molecular for the immune regulation of glioma." (PMID 37610668, 2023). "That means the SLC31A1 gene might influence the glioma progression by reshaping the immune microenvironment." (PMID 37610668, 2023). "We found that the SLC31A1 has great prognostic predicted efficiency in glioma patients." (PMID 37610668, 2023). "SLC31A1-related targeting may be a viable treatment approach in glioma in combination with immunotherapy." (PMID 37610668, 2023). "The results indicate the SLC31A1 gene is correlated with bad outcomes in glioma patients." (PMID 37610668, 2023). "Thus, it is plausible that the SLC31A1 gene defect may debilitate antitumor immune effects for glioma." (PMID 37610668, 2023). "And the SLC31A1 gene might be important for the resistance of apoptosis in glioma." (PMID 37610668, 2023). "Furthermore, Cox regression analysis in the TCGA database showed that FDX1, LIPT1, DLD, DLAT, SLC31A1, ATP7A, and DLST might be risk factors; however, LIAS, ATP7B, and GCSH were significant preventive factors for gliomas." (PMID 37515314, 2023). "This means the SLC31A1 may function by promoting the proliferation and migration of glioma cells." (PMID 37610668, 2023). "The medications targeting SLC31A1 may be helpful for the treatment of glioma." (PMID 37610668, 2023). "It has been shown that the SLC31A1 gene may play a key role in glioma." (PMID 37610668, 2023). "We hypothesize that the SLC31A1 gene can promote the progression of glioma." (PMID 37610668, 2023). "The results show a strong correlation to immune response, which is a strong influence factor of glioma progression; then, we further investigated the correlation between SLC31A1 and the TME of glioma." (PMID 37610668, 2023). "We further confirmed the abnormal expression of FDX1, SUMF1, and SLC31A1 proteins in glioma samples by immunohistochemistry, and the correlation between high expression of FDX1 protein and poor prognosis in glioma patients." (PMID 36856182, 2023). "The expression of GLS (p < 0.001), LIPT1, FDX1, SLC31A1 (p < 0.01), DLST, CDKN2A, PDHA1, ATP7A, ATP7B, and NFE2L2 (p < 0.05) was different between glioma and adjacent tissues." (PMID 36936439, 2023). "Only GLS and ATP7B had low expression levels in glioma patients; however, others, including FDX1, LIPT1, DLD, and SLC31A1, were overexpressed." (PMID 37515314, 2023). "As we analyzed, in GBM, the SLC31A1 gene expression positively correlates with M2 macrophage infiltration but negatively correlates with M1 macrophage infiltration, which may cause immune-suppressive TME formation and promote the immune escape of the glioma cells." (PMID 37610668, 2023). "Then, we further tested the SLC31A1 protein expression level by using data from the CPTAC database (N = 10, T = 100), and we found that the SLC31A1 protein is upmodulated in glioma samples (p = 0.0205)." (PMID 37610668, 2023). "Our result showed that the high expression level of SLC31A1 and low expression of ATP7B were found in more aggressive gliomas, which indicate high influx and low efflux of copper, resulting in copper retention in these tumors." (PMID 36267281, 2022).
glioma (continued). "SLC31A1 gene expression correlates positively with immunosuppressive M2 macrophage infiltration, but negatively with pro-inflammatory M1 macrophage infiltration, which may lead to the formation of an immunosuppressive TME in gliomas." (PMID 39062119, 2024). "Firstly, the function of the SLC31A1 gene in the glioma microenvironment is still not clear." (PMID 37610668, 2023). "Also, the SLC31A1 expression level is higher in patients with IDH WT status (WT = 246, Mut = 440) and 1p/19q non-codeletion (codel = 171, non-codel = 518), which were proven to have a strong correlation with unfavorable prognostic outcomes in glioma patients (p < 0.01)." (PMID 37610668, 2023). "However, in glioma, the SLC31A1 has not been studied in detail." (PMID 37610668, 2023). "As we investigated, the cuproptosis-correlated gene SLC31A1 is related to the immune response, but whether and how it acts in the TME of glioma is not clearly investigated." (PMID 37610668, 2023).
pancreatic cancer (10 papers, 2019 to 2024). "As a key gene associated with copper metabolism disorder, SLC31A1 is of great value in the prognostic prediction of pancreatic cancer and colorectal cancer." (PMID 39315155, 2024). "According to further analysis, pancreatic cancer had the highest mutation rate of the SLC31A1 gene, and the methylation levels of the gene were significantly reduced in seven tumors." (PMID 38001885, 2023). "In previous study, SLC31A1-dependent copper level was associated with the degree of malignancy of pancreatic cancer." (PMID 37424068, 2023). "Research has shown that the SLC31A1 expression level was correlated with the malignant degree of pancreatic cancer." (PMID 37275369, 2023). "In pancreatic cancer, copper transporter 1 (SLC31A1) and copper chelator tetrathiomolybdate (TM) can promote autophagy and inhibit growth of cancer cells by reducing copper uptake." (PMID 36050740, 2022). "All these data indicated that the copper inhibition induced by TM or si‐Slc31a1 resulted in a significant increase in cellular autophagy in pancreatic cancer cells." (PMID 30706544, 2019). "Consistent with this, the expression of Slc31a1 was found significantly higher in pancreatic cancer than in matched normal tissues based on the analysis of the NCBI database (GSE16515)." (PMID 30706544, 2019). "Our data and bioinformatic analysis further revealed that the levels of Slc31a1 mRNA were negatively correlated with the survival time of pancreatic cancer patients." (PMID 30706544, 2019). "In this study, we revealed that the increased expression of SLC31A1 was responsible for the increase in copper in pancreatic cancer cells." (PMID 30706544, 2019). "This analysis showed that SLC31A1 interference resulted in a significant decrease in copper level in the cells, which is consistent with SLC31A1‐dependent nature of copper dysregulation in pancreatic cancer cells." (PMID 30706544, 2019). "In this study, we found that SLC31A1‐dependent copper absorption was elevated in pancreatic cancer samples." (PMID 30706544, 2019). "The results showed that the proliferation of pancreatic cancer cells was inhibited by si‐Slc31a1 in a time‐ and concentration‐dependent manner." (PMID 30706544, 2019). "In this study, we report that copper and SLC31A1 coexist at a higher level in pancreatic cancer, and their levels were negatively correlated with the survival time of the patients." (PMID 30706544, 2019). "It has been reported that copper is absorbed mainly by the cell surface transporter SLC31A1 in mammals, we performed quantitative RT‐PCR (qPCR) to detect the expression of Slc31a1 in pancreatic cancer and paracancer specimens." (PMID 30706544, 2019). "Copper suppression via SLC31A1 knock‐down or TM treatment repressed pancreatic cancer cell proliferation, migration, and invasion, which demonstrated that elevated copper plays an essential role in pancreatic cancer progression." (PMID 30706544, 2019). "SLC31A1‐dependent copper levels are correlated with the malignant degree of pancreatic cancer." (PMID 30706544, 2019). "Moreover, cell cycle analysis indicated that TM or si‐Slc31a1 increased the G0/G1 phase of pancreatic cancer cells." (PMID 30706544, 2019). "SLC31A1‐dependent copper blockage suppressed pancreatic cancer progression, which indicated that copper deprivation could be a potential therapeutic approach." (PMID 30706544, 2019). "Blocking copper absorption via TM or knock‐down of SLC31A1 could inhibit pancreatic cancer progression by rendering them in a dormant state; however, cell death was not increased." (PMID 30706544, 2019). "Given that SLC31A1 is a major transmembrane copper transporter and its expression is increased in pancreatic cancer, we knocked down Slc31a1 in Panc‐1 cells using a previously reported siRNA21, and determined the intracellular copper content using ICP‐MS assay." (PMID 30706544, 2019).
colorectal cancer (8 papers, 2016 to 2025). A primary or metastatic malignant neoplasm that affects the colon or rectum. "Dysregulation of SLC31A1, ATP7B, and ATP7A has been implicated in colorectal cancer and can affect copper homeostasis and tumor growth." (PMID 38898987, 2024). "We also analyzed different publicly available datasets in order to confirm changes of SLC31A1 gene expression in colorectal cancer." (PMID 27516958, 2016). "Finally, exon‐level expression analysis of SLC31A1 reveals differential expression of alternative transcripts in colorectal cancer and normal colonic mucosa." (PMID 27516958, 2016). "It was found that the mutation frequency of each regulator is relatively low, of which ATP7A showed the highest mutation rate, followed by ATP7B and LIPT1, while FDX1, CDKN2A, SLC31A1, and GCSH showed no mutation in all colorectal cancer tissues." (PMID 36248908, 2022). "DLST SLC31A1, LIPT1, and UBE2D1 are reported to regulate cuproptosis in sepsis, hepatocellular carcinoma, multiple myeloma, thyroid carcinoma, oral squamous cell carcinoma, rheumatoid arthritis, periodontitis, gastric cancer, colorectal cancer, and myocardial infarction." (PMID 40980812, 2025).
melanoma (8 papers, 2018 to 2025). A malignant, usually aggressive tumor composed of atypical, neoplastic melanocytes. "The contribution of copper to the activation of the BRAF/MEK/ERK signaling pathway in melanoma was demonstrated by the finding that the downregulation of SLC31A1 or mutations in MEK1, which disrupt copper binding, resulted in decreased levels of phosphorylated ERK in BRAF-mutant melanomas." (PMID 39970778, 2025). "The combination of correlation analysis and prognosis analysis indicated that the expression of most cuproptosis-related genes was positively correlated with each other, and three genes (LIPT1, PDHA1, and SLC31A1) had a prognostic value in melanoma." (PMID 35837286, 2022). "They discovered that 11 out of 12 genes were upregulated in melanoma tissues and that three genes (LIPT1, PDHA1, and SLC31A1) have predictive value for the prognosis." (PMID 36454396, 2022).
liver cancer (6 papers, 2022 to 2024). An epithelial or non-epithelial malignant neoplasm that arises from the liver. "Cu transporter-related genes such as ATP7A, ATP7B, and SLC31A1 were singularly expressed or copied in liver cancer samples and a relative higher level of Cu was observed in HCC cell." (PMID 36438201, 2022). "In addition, the relative abundance of SLC31A1 protein in liver cancer and stomach cancer showed a significant difference between tumor tissues and adjacent normal tissues (P < 0.0001), in line with the mRNA expression difference." (PMID 36973786, 2023). "Expression of the Cu transporter genes ATP7A, ATP7B, SLC31A1 and SLC31A2 were found significantly altered in liver cancer samples with elevated Cu levels." (PMID 37324184, 2023). "The increase in copper content in liver cancer cell tissue is due to the loss of ATP7B, rather than SLC31A1 and SLC31A2 down-regulation; and in the liver, the lack of ATP7B affects its cell cycle and lipid metabolism." (PMID 38200525, 2024). "Moreover, we used the Kaplan–Meier plotter tool to analyze the overall survival of patients with liver cancer based on the expression of the FDX1, DBT, GCSH, SLC31A1, and DLAT genes." (PMID 37763758, 2023).
osteosarcoma (6 papers, 2020 to 2025). A usually aggressive malignant bone-forming mesenchymal neoplasm, predominantly affecting adolescents and young adults. "For example, in osteosarcoma, silencing SLC31A1 via siRNA reverses cisplatin resistance by reducing copper ion uptake." (PMID 41216190, 2025). "To further explore the role of SLC31A1 in osteosarcoma, we assessed the level of SLC31A1 in osteosarcoma tissues and CISR osteosarcoma cells." (PMID 32207235, 2020). "Then, we demonstrated that PTBP1 knock‐down enhanced the chemosensitivity of cisplatin‐resistant osteosarcoma cells to cisplatin by directly up‐regulating the expression level of SLC31A1." (PMID 32207235, 2020). "As expect, these data suggest that SLC31A1 mediates the effect of PTBP1 knock‐down on the chemosensitivity of CISR osteosarcoma cells by regulating the uptake of cisplatin." (PMID 32207235, 2020). "The results implied that PTBP1 knock‐down in cisplatin‐sensitive osteosarcoma cells also increased the expression of SLC31A1." (PMID 32207235, 2020). "In this study, we demonstrated the biological roles of PTBP1 and SLC31A1 in chemoresistant osteosarcoma for the first time." (PMID 32207235, 2020). "We further confirmed that SLC31A1 expression is lower in cisplatin‐insensitive osteosarcoma tissues and CISR cells." (PMID 32207235, 2020). "SLC31A1 is a trans membrane protein maintaining copper homeostasis that has been recently reported to negatively contribute to cisplatin resistance in various cancers including osteosarcoma and epithelial ovarian cancer." (PMID 37884650, 2023). "Furthermore, we validated the regulatory effect of PTBP1 on the expression of SLC31A1 and chemosensitivity enhanced by PTBP1 knock‐down is mediated by SLC31A1 in CISR osteosarcoma cells through a series of assays." (PMID 32207235, 2020). "Consequently, from the perspective of post‐transcriptional regulation, we identified SLC31A1 as the target of PTBP1 in CISR osteosarcoma cells by transcriptome sequencing, RIP assay and luciferase reporter assay." (PMID 32207235, 2020). "The results of qRT‐PCR analysis showed that the expression of SLC31A1 mRNA was down‐regulated in osteosarcoma tissues, especially lower in chemotherapy‐insensitive osteosarcoma tissues, and there was a negative correlation between the expression of SLC31A1 and PTBP1 in osteosarcoma tissue." (PMID 32207235, 2020). "PTBP1 affects the expression level of SLC31A1 by binding to its mRNA, thereby affecting the uptake of cisplatin by CISR osteosarcoma cells and regulating the sensitivity of CISR osteosarcoma cells to cisplatin." (PMID 32207235, 2020). "Together, these results suggest that the expression of SLC31A1 is decreased in chemotherapy‐insensitive osteosarcoma tissues and CISR osteosarcoma cells, and the effect of PTBP1 knock‐down on SLC31A1 up‐regulation is not unique to CISR cells." (PMID 32207235, 2020). "However, the role of SLC31A1 in cisplatin‐resistant osteosarcoma remains unclear." (PMID 32207235, 2020).
cervical cancer (5 papers, 2016 to 2024). A primary or metastatic malignant neoplasm involving the cervix. "As an influential player in the cuproptosis gene family, SLC31A1 has been confirmed to be highly correlated with poor prognosis in a range of tumor types, including BC, cervical cancers, head and neck squamous cell carcinoma, and esophageal carcinoma (ESCA) 63,78." (PMID 39309446, 2024).